NLRP6 (NLR family pyrin domain containing 6)
Diseases named in the same sentence as NLRP6 in open-access papers (continued):
Sharing a sentence is not in itself a finding about the gene and the disease.
myelodysplastic syndrome (1 paper, 2025). A clonal hematopoietic disorder characterized by dysplasia and ineffective hematopoiesis in one or more of the hematopoietic cell lines. "This study investigated the expression levels of NLRP6, IL-1β and IL-18 in patients with myelodysplastic syndrome (MD) and their potential diagnostic value." (PMID 40837366, 2025).
nephrotic syndrome (1 paper, 2026). A collection of symptoms that include severe edema, proteinuria, and hypoalbuminemia; it is indicative of renal dysfunction. "Here, we first observed only NLRP6 expression change in nephrotic syndrome patients with proteinuria." (PMID 41608624, 2026).
nonalcoholic fatty liver (1 paper, 2023). "However, this seems contradictory because NLRP6 is a protective factor for nonalcoholic fatty liver; thus, we assume that this is due to differences in genetic background." (PMID 35651286, 2023).
ovarian carcinoma (1 paper, 2023). A malignant neoplasm originating from the surface ovarian epithelium. "However, some PYAGs with CNV gain, such as GSDMD, TP63, PRKACA, PJVK and CASP4, showed downregulated mRNA expression in ovarian cancers, and some PYAGs with CNV loss, such as IL18, GPX4, GZMA, NLRP6 and CASP6, showed upregulated mRNA expression in ovarian cancers." (PMID 36707884, 2023). "Therefore, we performed methylation analysis of 51 PYAGs and showed that AIM2, CASP1, CASP8, GSDMC and NLRP6 exhibited hypomethylation in ovarian cancer, which may provide a new theory to explore the methylation of above five genes to improve potential antitumor efficacy of OC." (PMID 36707884, 2023).
overactive bladder (1 paper, 2021). Symptom of overactive detrusor muscle of the urinary bladder that contracts with abnormally high frequency and urgency. "Our study revealed that low-dose CYP treatment induced nerve injury in the bladder, which leading to pain in the lower abdomen and overactive bladder in female rats, and the up-regulation of mRNA expression levels of Nlrp6 and Casp11 may promote these pathological changes." (PMID 34658764, 2021).
prostate carcinoma (1 paper, 2017). A carcinoma that arises from epithelial cells of the prostate gland. "Using Gene Expression Omnibus (GEO) public datasets, we screened the expression profiles of inflammasome sensors NLRP3, NLRC4, NLRP6, NRLP12, and AIM2 in prostate tumor tissues, and verified their mRNA level in a panel of prostate cancer cell lines." (PMID 28663562, 2017). "We found that the mRNA level was very much variable across the cell lines, and there was no consensus on the expression levels of NLRP3, NLRC4, NLRP6, and AIM2 among early stage (e.g. LNCaP and LNCaP-Ln3) and late stage (e.g. PC3 and DU145) prostate cancer cell lines." (PMID 28663562, 2017).
pterygium (1 paper, 2023). A wedge-shaped fibrovascular lesion arising from the bulbar conjunctiva and extending to the cornea. "Activation of NLRP3 inhibits the activation of NLRP6 in normal conjunctival and pterygium tissues." (PMID 36993972, 2023). "In addition, studies have shown a negative correlation between the expression of NLRP3 and NLRP6 in normal conjunctiva and pterygium." (PMID 36993972, 2023).
Rotavirus infection (1 paper, 2025). Infection with any of the rotaviruses. "In mouse IECs from Trim29fl/fl mice, both NLRP6 and NLRP9b underwent more pronounced K48-linked ubiquitination when compared with IECs from Trim29IEC-KO mice following with EMCV or rotavirus infection." (PMID 39396665, 2025). "Additionally, although NLRP6 and NLRP9b were barely expressed in human HT-29 IECs, NLRP6 and NLRP9b were induced in HT-29 IECs after EMCV and rotavirus infection, respectively, suggesting thatNLRP6 and NLRP9b control the upregulation of IFN-λ3 and IL-18 upon knock down of TRIM29." (PMID 39396665, 2025).
schistosomiasis (1 paper, 2020). An infectious disease caused by parasitic trematodes of the genus Schistosoma that colonize human blood vessels and release eggs that can cause granulomatous reactions leading to acute (swimmer's itch or acute schistosomiasis syndrome) or chronic disease. "Our findings suggest that the NLRP6 inflammasome is an important component for schistosomiasis-associated pathology." (PMID 32431709, 2020).
steatosis (1 paper, 2022). Increased lipid within the cytoplasm of cells. "Interestingly, enhancing NLRP6 activity by virus-mediated overexpression of NLRP6 was shown to reduce liver steatosis, inflammation, and injury in alcohol-fed mice, suggesting a protective role of the NLRP6 inflammasome during ALD." (PMID 35053298, 2022). "While another study also claimed that NLRP6 activity negatively regulates NASH progression, the authors showed only enhanced liver damage upon constitutive Nlrp6 deficiency and did not further investigate other parameters of disease progression such as steatosis, inflammation, or fibrosis." (PMID 35053298, 2022). "While the authors reported reduced liver damage, steatosis, and fibrosis upon NLRP6 overexpression, we did not observe any alteration in these disease characteristics upon abrogation of endogenous NLRP6 activity in our long-term chronic-plus-binge model of ALD." (PMID 35053298, 2022).
tendinitis (1 paper, 2024). Inflammation of a tendon, usually resulting from an overuse injury. "Our analysis revealed a distinct expression profile of inflammasome-related genes in tendinitis, with NLRP6, NLRP1, and MEFV showing significant correlations with immune checkpoint molecules." (PMID 38919626, 2024).
Type 1 diabetes (1 paper, 2023). "NLRP6-deficient mice exhibited an expansion of CD103+ B cells and were protected from type 1 diabetes." (PMID 36911699, 2023). "We generated NLRP6-deficient Non-obese diabetic (NOD) mice to study the effect of NLRP6-deficiency on the immune cells and susceptibility to Type 1 diabetes development." (PMID 36911699, 2023).
viral myocarditis (1 paper, 2025). Myocarditis that is caused by an infection with a viral agent. "TRIM29 can target NLRP6 and NLRP9b to modulate intestinal inflammation, mitigate viral myocarditis by attenuating PERK-driven ER stress, and negatively regulate type I IFN responses to RNA viruses." (PMID 39973927, 2025).
infection (58 papers, 2013 to 2026). The state of being infected such as from the introduction of a foreign agent such as serum, vaccine, antigenic substance or organism. "In contrast, IL-18 and IL-22 independent signaling through Nlrp6 underlies only a modest, infection-induced increase in mucin secretion from goblet cells in the distal colon." (PMID 39428744, 2024). "In mice, NLRP6 deficiency or mutations in the LLPS region can lead to reduced activation of inflammasomes during infection with mouse hepatitis virus or rotavirus, indicating the anti-microbial immune function of NLRP6 LLPS." (PMID 37251408, 2023). "Future studies will have to determine the underlying mechanisms of NLRP6 activation and immune signaling during infections." (PMID 36761775, 2023). "It is meaningful that during the infection of K. pneumoniae, NLRP6 gene-deficient mice show the low levels of neutrophil recruitment, CXC chemokine and granulocyte factor." (PMID 36506034, 2022). "NLRP6 exhibits diametrically opposite functions for different pathogenic infections and even in different organs or cells." (PMID 35694317, 2022). "NLRP6 exhibits diverse functions in the regulation of responses against pathogenic infections and gut homeostasis." (PMID 33910012, 2021). "Recently, researchers observed that the gastrointestinal symptoms induced by infection, including reduced motility and loss of intestinal neurons, were mediated by a NLRP6- and CASP11-dependent mechanism." (PMID 34658764, 2021). "Therefore Nlrp6-independent inflammasome signaling mechanisms must underlie the robust goblet cell responses at these sites during infection." (PMID 39428744, 2024). "Early studies concluded that NLRP6-deficient mice were more resistant to infection with Listeria monocytogenes, Salmonella typhimurium, and Escherichia coli given by intravenous or intraperitoneal routes of infection." (PMID 33372132, 2021). "Furthermore, we investigated the participation of the gut microbiota from Nlrp6 deficient mice, on the gut permeability and Ba infection." (PMID 33617596, 2021). "In this issue of The EMBO Journal, Boegli and colleagues uncover a previously unrecognized role of the enigmatic innate immune sensor NLRP6 in detecting bacteria-induced lysosomal damage and triggering cytokine release or cell death to limit infection." (PMID 41266654, 2026). "Nevertheless, our characterization of the activation mechanism and the domains involved lays the groundwork for exploring NLRP6 function in these more complex endogenous systems, and to deciphering the contribution of NLRP6 to infection and autoinflammation." (PMID 41266655, 2026). "This way, the only route of infection for NLRP6 and ASC-expressing cells is through cell-to-cell spread, thus allowing us to determine if secondary infections are sufficient to activate NLRP6." (PMID 41266655, 2026). "It is also thought that NLRP6 binds to LTA from L. monocytogenes during infection in bone marrow-derived macrophages, triggering inflammasome activation." (PMID 41062723, 2025). "Treatment with propolis has been shown to enhance NLRP6 inflammasome activation, thereby aiding in the control of infection." (PMID 41060041, 2025). "An earlier study revealed that Nlrp6−/− mice produced similar levels of IL-1β following infection with S. Typhimurium, Listeria monocytogenes, and E. coli as wild-type mice did." (PMID 41062723, 2025). "While less dramatic, the distal colon-derived b2 mucus layer also significantly increased in thickness upon infection, in part reflecting an Nlrp6 inflammasome-dependent response." (PMID 39428744, 2024). "In response to infection by viruses, such as RNA viruses, NLRP6 inflammasome aims to regulate the expression of numerous IFN-stimulated genes through the mitochondrial adaptor protein MAVS." (PMID 38644450, 2024). "The results demonstrated that only the transcription levels of Zbp1 and Nlrp6 were upregulated in all five cell lines upon oHSV infection." (PMID 38693119, 2024).
infection (continued). "Western blotting analysis further confirmed the upregulation of ZBP1 and NLRP6 at the protein level in all five cell lines upon oHSV infection." (PMID 38693119, 2024). "Intraperitoneal infection with encephalomyocarditis virus and murine norovirus 1 leads to increased mortality and viremia in NLRP6-/- mice." (PMID 37515138, 2023). "This suggests that the inflammasome activation by direct binding of cytosolic LTA to NLRP6 contributes to the progression of intracellular infection by Listeria monocytogenes." (PMID 36977666, 2023). "During the infection of the lungs and intestines with different microbes, NLRP6 exhibits a dissimilar effect." (PMID 36556283, 2022). "The results show that Nlrp6−/− mouse macrophages secreted less GSDMD than WT macrophages during infection, which demonstrates that NLRP6 is involved in the modulation of pyroptosis." (PMID 36224650, 2022). "NOD-like receptor family pyrin domain containing 6 (NLRP6) plays an important role in the host innate immune response against pathogen infections." (PMID 35694317, 2022). "It was suggested that NLRP6 hurt the pulmonary host anti-Brucella defense when the two infections occurred at the same time." (PMID 36556283, 2022). "During the infection of the lungs and intestines with different microbes, NLRP6 exhibited a dissimilar effect." (PMID 36556283, 2022). "The results show that the secretion levels of IL-1β and IL-6 from the BALF and serum of Nlrp6−/− mice were significantly lower than those of WT mice after infection, while the secretion levels of TNF-α did not change." (PMID 36224650, 2022). "NLRP6 inflammasome signaling in the intestinal goblet cells stimulates autophagy required for mucus production and resistance to infection." (PMID 34401074, 2021). "The results showed that the secretion of IL-1β was partially dependent on activation of NLRP6 inflammasome during macrophages infection with S. pneumoniae." (PMID 33918100, 2021). "The number of bacterial numbers in the lungs of WT mice were much higher than in those of NLRP6−/− mice at 48 h post infection." (PMID 33918100, 2021). "B. abortus CFU amounts were also found reduced in the liver from Nlrp6-/- mice at late time point (7 days after infection) compared to WT mice." (PMID 33617596, 2021). "The activation of NLRP6 by LTA, originating from pathogenic bacteria, leads to excessive IL-18 release, which exacerbates infection." (PMID 34948270, 2021). "We showed that infection of Nlrp6−/− mice with Citrobacter rodentium resulted in reduced caspase-1 activation and IL-18 processing." (PMID 33910012, 2021). "NLRP6, preferentially expressed in goblet cells and enterocytes, is involved in similar processes: host defense against infection, autoimmune responses, tumorigenesis, and intestinal homeostasis." (PMID 34948270, 2021). "Similar findings have been reported for NLRP6 and NLRP12 to play a pathogenic role during infection with Brucella abortus, S. Typhimurium, and Plasmodium chaubadi." (PMID 34690967, 2021). "Consistently, the frequency of macrophage and neutrophil populations were lower in the liver of NLRP6 knockout mice, after 6 weeks of infection." (PMID 32431709, 2020). "The level of expression of NLRP6 inflammasome remained similar following infection with virulent and less-virulent strains of HSV-1." (PMID 31367214, 2019). "Collectively, these results indicate that the production of IL-18, while mediated by NLRP6 in the initial phase of infection, is then dependent on NLRC4, more than NLRP3." (PMID 31681274, 2019). "To determine if neutrophils confer augmented host protection in NLRP6 KO mice, we depleted neutrophils in the KO mice prior to infection with a lethal dose of S. aureus and observed survival." (PMID 30248149, 2018). "To this end, we compared the intracellular killing ability of bone marrow derived-neutrophils (BMDNs) and BMDMs isolated from both WT and NLRP6 KO mice following infection with S. aureus (MOI:10)." (PMID 30248149, 2018).
infection (continued). "Although all WT mice died within 3 days, 70% of NLRP6 KO mice survived longer than 10-days post-infection." (PMID 30248149, 2018). "To this end, we performed flow cytometric analysis of lung cells from WT and KO mice following infection with S. aureus and found that NLRP6 KO mice had more IFN-γ-positive NK and CD4+T cells." (PMID 30248149, 2018). "The NLRP6 KO mice also displayed decreased pyroptosis and necroptosis in the lungs following infection." (PMID 30248149, 2018). "To validate that NLRP6 induces pyroptosis, we assessed the expression of caspase-1 and gasdermin-D in BMDMs from WT and NLRP6 KO mice after infection with S. aureus (MOI of 20) for 8 hours." (PMID 30248149, 2018). "Consistent with the in vitro results, NLRP6 KO mice showed lower levels of IL- 1β in bronchoalveolar lavage fluid (BALF) after infection with S. aureus, providing evidence of NLRP6 inflammasome activation in vivo." (PMID 30248149, 2018). "Nlrp6 has been shown to play critical roles in defense against infection and tumorigenesis and in maintaining intestinal homeostasis and a healthy, equilibrated intestinal microbial flora." (PMID 26253422, 2015). "NLRP6 acting as a sensor for secondary infection was elegantly confirmed when uninfected, NLRP6-expressing HEK293T cells were seeded onto infected NLRP6-deficient HEK293T cells in antibiotic-containing media (which ruled out secondary infection via an extracellular route) and became activated." (PMID 41266654, 2026). "We found that after a reinfection period of 14 h, only WT bacteria that were able to spread from cell to cell activated NLRP6, while the immotile ΔactA mutant caused no NLRP6 activation, thus supporting our conclusion that secondary infection activates NLRP6." (PMID 41266655, 2026). "After infection clearance, the NLRP6 inflammasome needs to be down-regulated." (PMID 38644450, 2024). "In addition, Nlrp6 is targeted by both mouse (miR-212-5p) and Fasciola (miR-71a) miRNAs at both 6 and 18 hrs post-infection." (PMID 39344634, 2024). "In localized infection models such as intestinal and pulmonary inflammation where neutrophils are important to clear pathogens, NLRP6 could play a crucial role; however, in the septic model, NLRP6-induced inflammation is detrimental." (PMID 38720893, 2024). "Mediating a similar outcome, Nlrp6 (the most downregulated innate gene at 6hrs post-infection; −30.2 fold) acts as a cytosolic sensor in macrophages and mediates the secretion of pro-inflammatory cytokines IL-18, IL-1β and TNF in response to ligand stimulation." (PMID 39344634, 2024). "Interestingly, Nlrp6-/- mice are more resistant to infection with Listeria monocytogenes, Salmonella Typhimurium and Escherichia coli, demonstrating NLRP6 can act as a negative regulator in innate immune signaling and host defense." (PMID 36761775, 2023). "This indicated that an infection with B. Suis and/or IAV could cause NLRP6 to be activated in the lungs of mice, which could exert a proinflammatory effect." (PMID 36556283, 2022). "Moreover, Nlrp6-/- mice were more resistant to infection, with decreased CFU in the liver and reduction in gut permeability when compared to the control group." (PMID 33617596, 2021). "Similarly, our study showed that NLRP6 mediates the secretion of IL-1β and IL-6 during macrophages infection with S. pneumoniae." (PMID 33918100, 2021). "NLRP6-deficient mice are also more susceptible to oral (but not intraperitoneal) infection with mouse norovirus." (PMID 33372132, 2021). "Thus, it is likely that the protective role of NLRP6 during the initial phase of infection in VVC is stimulated by the vaginal microbiome with the production of IL-18." (PMID 31681274, 2019). "To determine if differences in killing ability of WT and NLRP6 KO neutrophils is due to an alteration in ROS production, we compared ROS production by neutrophils from WT and KO mice after infection with S. aureus and found that KO neutrophils produced more ROS than WT neutrophils." (PMID 30248149, 2018).